LPAR2 (lysophosphatidic acid receptor 2)
Description:
Receptor for lysophosphatidic acid (LPA), a mediator of diverse cellular activities. Seems to be coupled to the G(i)/G(o), G(12)/G(13), and G(q) families of heteromeric G proteins. Plays a key role in phospholipase C-beta (PLC-beta) signaling pathway. Stimulates phospholipase C (PLC) activity in a manner that is independent of RALA activation.
Synonyms: LPA-2; EDG4; LPA2; EDG-4
Tractability: Small molecule: a high-quality ligand is known; it belongs to a druggable protein family. Antibody: UniProt places it where antibodies can reach, with high confidence; its Gene Ontology location is reachable by antibodies, with high confidence; UniProt predicts a signal peptide or a membrane-spanning region. PROTAC: a small molecule that binds it is known.
Target class: EDG receptor; Family A G protein-coupled receptor; Lipid-like ligand receptor (family A GPCR); Membrane receptor; Small molecule receptor (family A GPCR)
Gene: Protein-coding gene on chromosome 19 (19,623,639 to 19,628,930, reverse strand). Ensembl gene ENSG00000064547.
Subcellular location: Cell surface; Cell membrane
Pathways (Reactome):
Signal Transduction: G alpha (i) signalling events; G alpha (q) signalling events; Lysosphingolipid and LPA receptors
Gene Ontology:
Molecular function: protein binding; G protein-coupled receptor activity; lipid binding; lysophosphatidic acid receptor activity; PDZ domain binding
Biological process: G protein-coupled receptor signaling pathway; adenylate cyclase-activating G protein-coupled receptor signaling pathway; positive regulation of cytosolic calcium ion concentration
Cellular component: cell surface; endocytic vesicle; cytoplasm; plasma membrane; glutamatergic synapse; membrane; presynaptic active zone membrane
Genetic constraint (gnomAD): Loss-of-function variants: 10 observed, 17.36 expected, observed/expected ratio (o/e) 0.58, 90% interval 0.35 to 0.98. The upper end of that interval is the gene's LOEUF score, 0.98, which puts it in group 4 of 6, group 1 being the genes least tolerant of losing a copy. Missense variants: 336 observed, 392.95 expected, observed/expected ratio (o/e) 0.86, 90% interval 0.78 to 0.94. Synonymous variants: 175 observed, 174.21 expected, observed/expected ratio (o/e) 1, 90% interval 0.89 to 1.14.
Homologues: Orthologues: chimpanzee LPAR2 (99% identical), macaque LPAR2 (99% identical), dog LPAR2 (96% identical), pig LPAR2 (96% identical), rat Lpar2 (93% identical), guinea pig LPAR2 (93% identical), mouse Lpar2 (92% identical), rabbit LPAR2 (75% identical), tropical clawed frog lpar2 (62% identical), zebrafish lpar2b (56% identical), zebrafish lpar2a (50% identical). Paralogues in human: LPAR1 (52% identical), LPAR3 (45% identical), S1PR4 (34% identical), S1PR1 (34% identical), S1PR5 (33% identical), S1PR2 (32% identical), S1PR3 (30% identical), GPR3 (26% identical), GPR6 (26% identical), GPR12 (24% identical), CNR1 (23% identical), MC5R (23% identical), and 6 more.
Diseases named in the same sentence as LPAR2 in open-access papers:
LPAR2 is named in the same sentence as 95 diseases in open-access papers, as found by Europe PMC text mining. Sharing a sentence is not in itself a finding about the gene and the disease. The quoted sentences say what the papers report.
ovarian carcinoma (24 papers, 2009 to 2024). A malignant neoplasm originating from the surface ovarian epithelium. "For ovarian cancer, tumors with overexpression of LPAR2 were associated with poorer survivals compared with controls." (PMID 34209775, 2021). "Although the precise mechanisms linking LPA and proliferation of tumor cells are not fully understood, a recent study has implicated the LPA/LPAR2 signaling in promotion of glucose metabolism in cancer cells, which in turn triggers ovarian cancer cell proliferation." (PMID 31049165, 2019). "LPA inhibits taxol-induced apoptosis in melanoma and breast cancer cells and cisplatin-induced apoptosis in ovarian cancer cells through LPAR2." (PMID 31652837, 2019). "The relevance of LPA2 to carcinogenesis has been suggested early on by the findings that LPAR2 gene expression is elevated in ovarian cancer and thyroid cancer." (PMID 31323936, 2019). "Overall, these data suggest LPAR2‐specific regulation of invasion in ovarian cancer cells through ETS‐1." (PMID 28236660, 2017). "We also found Gi‐LPAR2 activation to be significantly responsible for ETS‐1‐mediated ovarian cancer tumorigenesis." (PMID 28236660, 2017). "In our study, we also found that the expression rate of LPAR2 increased in ovarian cancer than in normal specimens." (PMID 27809800, 2016). "The expression rate of LPAR2 was much higher in ovarian cancer specimens than in normal ones (P = 0.039)." (PMID 27809800, 2016). "LPAR2 has been linked to specific receptor-interacting proteins such as TRIP-6, through which it induces ovarian cancer cell migration." (PMID 23426604, 2013). "LPARs are overexpressed in ovarian cancer cells and tissues, specifically, LPAR2 and LPAR3." (PMID 40836974, 2024). "By contrast, others showed that LPAR2 knockdown reduced p-ERK levels in ovarian cancer cell lines." (PMID 34440828, 2021). "In early work, Goetzl and co-workers investigated the expression and function of Edg family receptors (including those activated by sphingosine 1-phosphate) in primary ovarian cultures and ovarian cancer cell lines, with a focus on LPAR2, which was upregulated in cancer cells." (PMID 34440828, 2021). "Indeed, LPAR1 is crucial in bone metastasis of breast carcinoma, LPAR2 promotes colorectal cancer and aggressiveness of ovarian cancer cells, whereas LPAR3 enhances migration of hepatoma cells (and refer therein)." (PMID 31652837, 2019). "Moreover, the expression rate of LPAR2 significantly increased in ovarian cancer than in normal specimens (P = 0.039)." (PMID 27809800, 2016). "Particularly, LPAR2 and LPAR3 have been shown to be frequently overexpressed in ovarian cancer cells and tissues." (PMID 35625966, 2022). "Expression of LPAR2 and LPAR3 has been correlated with increased cell aggressiveness in ovarian cancer." (PMID 34440828, 2021). "The qRT-PCR results showed that LPAR1, LPAR2, and LPAR3 were positive in 75.00 %, 12.50 %, and 6.25 % in the 15 of the normal ovarian specimens, respectively; and 69.23 %, 42.31 %, 17.31 % in the 52 of the ovarian cancer specimens, respectively." (PMID 27809800, 2016). "LPAR2 and LPAR3 might play an role in carcinogenesis of ovarian cancer." (PMID 27809800, 2016). "However, in our study, we demonstrated that LPAR1 expression in invasive ovarian cancer cells was significantly higher than in non-invasive ones; while the expression of LPAR2 and LPAR3 had no statistical correlation with the metastatic potential of ovarian cancer cells." (PMID 27809800, 2016).
breast carcinoma (21 papers, 2004 to 2023). "The LPAR2 associated HIF-1α expression also promoted breast cancer proliferation/migration and conferred poor prognosis in the Chinese population." (PMID 34209775, 2021). "Regarding specific receptors, overexpression of LPAR1 and LPAR2 has been observed across breast cancers, as reported by several research groups." (PMID 34440828, 2021). "Expression of human ATX, LPAR1, LPAR2 or LPAR3 in transgenic mice is sufficient to induce late-onset mammary carcinomas." (PMID 31652837, 2019). "Taken together, these findings suggest that LPAR2 inhibition may have a unique specificity for mitigating breast cancer tumor progression." (PMID 37372960, 2023). "Proliferation and/or motility of cancer cells were promoted after LPA signalling through the LPAR1 in colon, gastric, and breast cancer, LPAR2 in colon and renal cancer, LPAR3 in colon, pancreatic, and breast cancer, LPAR4 in fibrosarcoma, and LPAR6 in hepatic and pancreatic cancer." (PMID 34722305, 2021). "In other tumors, such as colon cancer and breast cancer ect, LPAR2 promotes the migration, invasion, and proliferation of tumor cells through LPAR2-Gi-Src-EGFR-ERK signaling and HIF1α-LPA-LPAR2 Axis." (PMID 35769713, 2022). "It has been reported that breast cancer cells express elevated levels of LPAR1, LPAR2, and LPAR3 and that these LPA receptors are involved in stimulating tumorigenic and metastatic cascades via Wnt, MAPK, and PI3K pathways." (PMID 34440828, 2021). "Many groups have reported that expression levels of LPA receptors (LPAR1, LPAR2, and LPAR3) and/or β-arrestins are elevated in advanced stages of breast cancers." (PMID 34440828, 2021). "In transgenic mouse models, overexpression of each of these individual LPA receptors (LPAR1, LPAR2 and LPAR3) under the control of the mouse mammary tumour virus long terminal repeat (MMTV-LTR) promoter led to the formation of late-onset mammary carcinomas." (PMID 25572802, 2015). "Other studies from breast cancer cell lines indicated that both LPAR1 and LPAR2 mediated LPA-induced chemotaxis in breast carcinoma cells." (PMID 24744506, 2014). "A particularly important study by Liu and colleagues showed that overexpression of LPAR1, LPAR2, or LPAR3 in transgenic mice could induce mammary tumors." (PMID 34440828, 2021). "As opposed to LPAR1, we did not observe significant correlations between ZEB1 and LPAR2 or LPAR3 in publicly available breast cancer cell line databases." (PMID 26098771, 2015).
colon cancer (13 papers, 2015 to 2024). "In colon cancer cells, upregulation of LPAR2 and LPAR4 helps to overcome the oxidative stress induced by H2O2 and anticancer drugs such as 5′-fluoro-uracil, irinotecan and oxaliplatin." (PMID 38607068, 2024). "LPAR2 expression is upregulated in gastric and colon cancers, and also in dextrane sulfate sodium (DSS)-induced murine colitis, and inhibition of LPAR2 attenuates both colitis and tumor formation." (PMID 37816857, 2024). "LPAR2 is the major LPAR in colon cancer, and most of the cellular signals by LPAR2 were primarily mediated through interaction with scaffold proteins Na+/H+ exchanger regulatory factor 2 (NHERF2)." (PMID 34209775, 2021). "The altered expression of LPAR2 is a common occurrence in several colon cancer cell lines." (PMID 31323936, 2019). "LPA increases the expression of KLF5 to increase cell proliferation in colon cancer cells, and this LPA-induced KLF5 expression is mediated by LPAR2 and LPAR3." (PMID 36142408, 2022). "Moreover, LPAR2 and LPAR5 mediate resistance of colon cancer cells to 5′-fluoro-uracil, whilst in the same tumour type, LPA enhances resistance to EZH2 inhibitors through LPAR2, suggesting that co-targeting of ATX/LPA/LPAR2 and EZH2 might be beneficial for colon cancer treatment." (PMID 38607068, 2024).
gastric cancer (7 papers, 2013 to 2025). A primary or metastatic malignant neoplasm involving the stomach. "A few studies have suggested that LPAR2 is associated with several cancers, such as breast, colon, ovarian, and stomach cancers." (PMID 35241179, 2022). "In gastric cancer, LPAR2 reduces AXIN2 expression, activating the Wnt/β-catenin pathway and promoting cancer cells to be proliferated, migrated and invaded." (PMID 40746892, 2025). "The knockdown of LPAR2 in the gastric cancer cell lines robustly reduced the LPA-induced β-catenin activity." (PMID 36551233, 2022). "Data from another study have shown that LPAR-1, LPAR-2, and LPAR-3 are present in gastric cancer cell lines; among them, LPAR2 was expressed aberrantly in the AGS cell line." (PMID 36551233, 2022). "In agreement with this, the results from our clinical cohort studies revealed the high expression of LPAR2 in all stages of gastric cancer tissues compared to the expression in normal gastric tissues." (PMID 36551233, 2022). "The results demonstrate that the LPA-induced migration of SGC-7901 gastric cancer cells requires LPAR2." (PMID 23426604, 2013). "Several studies have reported that LPAR2 gene expression is increased in a variety of cancer cells, suggesting that LPAR2 is involved in gastric cancer." (PMID 23426604, 2013). "In the present study, the potential role of LPAR2 in gastric cancer SGC-7901 cell migration was evaluated." (PMID 23426604, 2013). "In addition, the immunohistochemical analysis of LPAR2 in the normal human stomach and primary tumor of the stomach tissue sections showed a significant increase in the LPAR2 expression in gastric cancer tissues." (PMID 36551233, 2022). "The present findings suggest that LPAR2 may be a potential target for the clinical treatment of gastric cancer." (PMID 23426604, 2013). "In addition, the LPAR2 mRNA level was increased in all stages of gastric cancer." (PMID 36551233, 2022). "However, LPAR2 has a similar role in gastric cancer cells, indicating that LPARs may have a cell specificity in their distribution and function." (PMID 23426604, 2013). "Here, we have noted the high expression of LPAR2 in human gastric cancer tissues, and that LPA treatment significantly increased the proliferation, migration, and invasion of human gastric cancer cells." (PMID 36551233, 2022). "In a gastric cancer cell line, LPA stimulates migration, invasion, and EMT via LPAR2; the investigative team also demonstrated physical interaction between LPAR2 and Notch1." (PMID 34440828, 2021). "Immunohistochemical analysis of LPAR2 has shown that LPAR2 expression is a significant process in gastric cancer progression, although the mechanism of LPA-induced gastric cancer cell migration is not fully understood." (PMID 23426604, 2013). "The present study reports that LPA stimulates the migration of human gastric cancer cells (SGC-7901) and the LPAR2/Gq/11/p38 pathway regulates this migration." (PMID 23426604, 2013). "In conclusion, LPAR2 is markedly expressed in SGC-7901 cells and, as a promising biomarker of gastric cancer, is critical in gastric cancer cell migration (invasion) in LPA-rich micro-environments." (PMID 23426604, 2013). "In this study, we demonstrated that LPA increased the proliferation and subsequent progression of the gastric cancer cells, which get abrogated into the functional level by both LPA receptor antagonists (Ki16425 and the LPAR2 receptor antagonist) and LPAR2 knockdown." (PMID 36551233, 2022). "The effect of LPA on gastric cancer migration with and without LPAR2 knockdown was then evaluated and the effect of LPA on migration was shown to be blocked in shLPAR2-transfected SGC-7901 cells." (PMID 23426604, 2013). "LPAR2 was observed to be highly expressed in SGC-7901 cells, a human gastric cancer cell line, while LPAR1 and LPAR3 were not." (PMID 23426604, 2013).
pulmonary fibrosis (7 papers, 2009 to 2025). Chronic progressive interstitial lung disorder characterized by the replacement of the lung tissue by connective tissue, leading to progressive dyspnea, respiratory failure, or right heart failure. "In agreement with a pathogenic role of ATX/LPA in pulmonary fibrosis, ubiquitous genetic deletion of either Lpar1 or Lpar2 also abrogated BLM-induced disease development." (PMID 29951481, 2018). "Expression of LPAR1 and 2 was implicated since bleomycin-treated mice lacking LPAR1 or LPAR2 were protected from developing lung fibrosis." (PMID 33794877, 2021).
colitis (4 papers, 2015 to 2024). Inflammation of the colon. "Previous studies have shown that LPA stimulates COX-2 expression and prostaglandin E2 production in a human gastric cell line expressing LPAR2, whereas intestinal COX-2 expression is lower in Lpar2−/− mice than in WT mice in a colitis-associated tumor model." (PMID 37816857, 2024). "It is plausible that more severe tissue inflammation at a later more advanced disease stage of enteropathy might overcome the direct effects of IND resulting in increased ATX and LPAR2 expression, similarly to the changes reported in inflammatory bowel disease and animal models of colitis." (PMID 37816857, 2024).
colorectal cancer (4 papers, 2016 to 2024). A primary or metastatic malignant neoplasm that affects the colon or rectum. "Hence, it is reasonable to assume that downregulation of ATX and LPAR2 is an additional mechanism underlying the anticancer effect of NSAIDs, at least in certain cancer types in which LPAR2 is upregulated, such as colorectal cancer." (PMID 37816857, 2024).
gastric tumor (4 papers, 2013 to 2022). "Subsequently, we performed the Western blotting analysis of LPAR1-3 receptors and we found that the LPAR2 protein expression was significantly increased (p < 0.001) in the human stomach tumor compared to the normal human stomach tissue." (PMID 36551233, 2022). "The present study contributes to the use of specific shLPAR2 to identify the mechanisms and functions of LPAR2 and to investigate LPA’s regulatory effect on the gastric tumor microenvironment." (PMID 23426604, 2013).
melanoma (4 papers, 2020 to 2023). A malignant, usually aggressive tumor composed of atypical, neoplastic melanocytes. "In addition to our finding that PCa patients in the high LPAR5 expression group had worse survival, other LPAR subtypes were associated with poor survival such as LPAR1 in melanoma, LPAR2 in adrenocortical carcinoma, LPAR3 in pancreatic cancer, and LPAR4 in renal papillary carcinoma." (PMID 36806315, 2023). "Specifically, TILs derived from three melanoma patients predominantly expressed LPAR6 with low expression of LPAR2, whereas peripheral CD8+ T cells expressed LPAR6 > LPAR2 > LPAR5 > LPAR4." (PMID 32397679, 2020). "Reversely, proliferation and/or motility of cancer cells also showed a decrease after LPA signalling through LPAR2 in melanoma, LPAR4 in pancreatic, colon, and head and neck cancer, LPAR5 in pancreatic cancer and melanoma, and LPAR6 in colon cancer." (PMID 34722305, 2021).
multiple sclerosis (4 papers, 2017 to 2022). A progressive autoimmune disorder affecting the central nervous system resulting in demyelination. "Lysophosphatidic acids are reduced in patients with multiple sclerosis and in EAE mice, and the consequent loss of LPAR2 signaling in immune cells promotes the disease." (PMID 28578681, 2017).
pancreatic cancer (4 papers, 2014 to 2023). "Several other studies have also shown that LPAR1 can promote the metastasis and invasion of pancreatic cancer cells, while LPAR2 has the opposite effect 81,82." (PMID 32284748, 2020). "LPAR2 was found to mediate LPA-induced invasion in endometrial cancer, but seemed to have an inhibitory role in pancreatic cancer." (PMID 24928086, 2014).
endometrial cancer (3 papers, 2013 to 2021). Primary or metastatic malignant neoplasm involving the endometrium (mucous membrane that lines the endometrial cavity). "LPAR2, in particular, has been shown to be upregulated in a variety of cancer types, including colon, gastric, ovary and endometrial cancer." (PMID 23426604, 2013). "The role of LPAR2 in the invasion of endometrial cancer cells has been investigated." (PMID 34440828, 2021). "A subsequent study compared the mRNA expression levels of LPAR1, LPAR2, and LPAR3 in human endometrial cancer samples to those in adjacent non-cancerous tissue." (PMID 34440828, 2021).
thyroid cancer (3 papers, 2019 to 2022). "However, LPAR2 expression was significantly lower in kidney chromophobe (KICH) and thyroid carcinoma (THCA) than in the adjacent normal tissues." (PMID 35241179, 2022).
adenoma (2 papers, 2016 to 2019). A neoplasm arising from the epithelium. "In ApcMin/+ mice, a mouse model of familial polyposis, LPAR2 mRNA level increases with increased size of adenomas, and oral administration of LPA increases adenomas growth." (PMID 31323936, 2019).
dysplasia (2 papers, 2016 to 2020). A usually neoplastic transformation of the cell, associated with altered architectural tissue patterns. "In a mouse model, overexpression of LPAR2 induces intestinal dysplasia, which therefore alters the proliferation and differentiation of the intestinal epithelial cells (IEC)." (PMID 32605309, 2020).